AHR (aryl hydrocarbon receptor)
Diseases named in the same sentence as AHR in open-access papers (continued):
Sharing a sentence is not in itself a finding about the gene and the disease.
viral infection (63 papers, 2011 to 2026). "Drug targeting AHR reduces virus replication in hamsters and reverses the pathological damage of lung inflammation caused by virus infection in vivo." (PMID 37256962, 2023). "Exploring the impact of different virus infections on the AHR pathway will help us understand the pathogenic mechanism of viruses regulating AHR and provide more precise, efficient, and potential therapeutic targets for antiviral therapy points." (PMID 36829212, 2023). "Taken together, these studies highlight the potential contributions of AHR polymorphisms to human disease, and call for future studies focused on the investigation of the role of these polymorphisms in viral infections." (PMID 33746961, 2021). "Investigating viral-specific modulation of the AhR pathway will advance our understanding of virally hijacked pathogenic mechanisms, thereby enabling discovery of precision-targeted therapeutic interventions against viral infections." (PMID 41150072, 2025). "In addition to the extensive survey conducted, numerous other viral infections are linked to the AhR signaling pathway, including BK polyomavirus, Zika virus, Junín virus, and others." (PMID 38680494, 2024). "Given that the production of IFNs is a ubiquitous host response following viral infection, the blockade of the AhR pathway to reduce mucin expression by epithelial cells may also be suitable to treat various viral infection-caused lung disorders such as SARS, MERS and Ebola." (PMID 33159154, 2020). "In recent years, the aryl hydrocarbon receptor (AHR) has gathered attention as a potential host-directed therapeutic target against viral infections." (PMID 41596714, 2026). "The results presented in this article further contribute to the growing evidence supporting AHR as a promising pharmacological target for the treatment of several viral infections." (PMID 41596714, 2026). "Our results show that CH223191 is a potent AHR antagonist with proven antiviral activity across several viral infection models." (PMID 41596714, 2026). "While there are currently no clinical trials evaluating the safety and efficacy of the AHR inhibitors for the treatment of viral infections, recent trials tested the AHR inhibitors IK-175 and BAY 2416964 for the treatment of solid tumors." (PMID 41596714, 2026). "This is the first report demonstrating significant protection against viral infections in mice afforded by treatment with an AHR antagonist." (PMID 41596714, 2026). "Overall, these studies suggest that AhR, as an immune regulatory molecule, is involved in the regulation of various viral infections and host immune responses." (PMID 40636257, 2025). "On the other hand, a recent study implied that lung endothelial AHR prevents lung barrier damage to response for viral infection." (PMID 40918440, 2025). "Recent studies have also confirmed that AhR regulates viral infection and immunity, thereby providing a survival advantage to many viruses." (PMID 40636257, 2025). "AhR activation suppresses the constant defensive function against viral infection by suppressing TBK1." (PMID 40807684, 2025). "In the context of viral infections, AhR signaling was shown to downmodulate IFN-I responses via the induction of TIPARP, which inhibits TANK-binding kinase 1 (TBK1) downstream of RIG-I activation, or by inhibiting NF-κB signaling." (PMID 41321306, 2025). "Previous work evidenced that AhR activation during viral infections suppresses IFN-I responses in macrophages." (PMID 41321306, 2025). "Analysis of gene and protein expression reveals that the expansion and function of CD4+ T cells are suppressed during viral infection due to increased AhR activation." (PMID 38680494, 2024). "The activation of AhR in the IFN/IDO/Kyn axis by the viral infection leads to lung inflammation, which subsequently promotes the expression of mucin production, intercellular adhesion, and cytokine release." (PMID 38680494, 2024).
viral infection (continued). "Taken together, these results identify endothelial-specific AHR activity as a host mechanism of lung barrier protection which prevents vascular leakage in air spaces upon viral infection." (PMID 37587341, 2023). "In general, our review discusses the relationship between virus infections and AHR pathways, providing an important direction for the future treatment of virus-associated diseases." (PMID 36829212, 2023). "Recent studies have confirmed that AhR regulates viral infection and replication through various pathways, thereby providing a survival advantage to many viruses." (PMID 37256962, 2023). "Drug targeting of AhR with AHR antagonists markedly reduced SARS-CoV-2 replication and reversed the pathological damage of lung inflammation caused by virus infection in hamsters." (PMID 37256962, 2023). "Pathway analysis revealed marked dysregulation in proliferation and cell-cell signalling in ECΔAhr epithelial cells, suggesting an extensive AHR-driven cross talk between the lung endothelium and epithelium following viral infection." (PMID 37587341, 2023). "Obviously, AhR signaling and other various pathways were significantly up-regulated after virus infection." (PMID 37256962, 2023). "We identify an additional layer of regulation underlying AHR lung function with the observation that protective AHR signalling is significantly depressed following viral infection." (PMID 37587341, 2023). "It is also worth mentioning that the involvement of AHR in viral infections extends beyond the cells, encompassing broader implications at the tissue and organ levels." (PMID 37672505, 2023). "The identification of AhR as a proviral host factor has therapeutic significance for infectious viral diseases." (PMID 37256962, 2023). "Several articles have reported that virus infections can affect the AHR signaling pathways, which play multiple roles in cells." (PMID 36829212, 2023). "Here, we mainly summarize the effects of several different virus infections on the AHR signaling pathways, and the effects of the AHR signaling pathway on virus replication and proliferation in turn." (PMID 36829212, 2023). "Most of the genes of significance in viral infections contain one or more AHR/NRF2 binding sites and some of them have both." (PMID 35629310, 2022). "PARP7 expression is induced by platelet-derived growth factors, viral infection, nuclear hormone receptors, hypoxia, and aryl hydrocarbon receptor (AHR)." (PMID 35055106, 2022). "AhR’s ability to modulate NF-κB during viral infections has been described in a paper by Giovannoni’s group." (PMID 35203299, 2022). "Because AHR activity can be regulated by small molecules, AHR is an attractive target for therapeutic immunomodulation in the context of virus infection." (PMID 33746961, 2021). "The aryl hydrocarbon receptor (AhR) is a cytoplasmic receptor/transcription factor modulating several cellular and immunological processes following viral infections." (PMID 34367175, 2021). "In summary, the AHR pathway has stepped into the spotlight for the treatment of several non-viral diseases." (PMID 33746961, 2021). "All the lessons being learnt from the development of drugs targeting AHR in the context of other diseases will likely impact the development of molecules targeting AHR to treat viral infections." (PMID 33746961, 2021). "The well-defined AHR pathway provides an excellent model to investigate the effects of the exposome on multiple aspects of physiology such as the response to viral infections." (PMID 33746961, 2021). "Evidence showing that AHR activation has a strong influence on host resistance to viral infection was first reported over 40 years ago." (PMID 33746961, 2021). "In this review, we will evaluate the role of AHR on the host response to viral infection and its potential as a candidate target for therapeutic intervention." (PMID 33746961, 2021).
viral infection (continued). "PARP-7 plays multiple essential roles in biological processes, such as transcription, RNA metabolism, translation in response to viral infections, and AHR activation." (PMID 33475085, 2021). "This review will focus on the increasing evidence supporting a role for AHR as a modulator of the host response to viral infection." (PMID 33746961, 2021). "Based on differential gene expression analysis, IPA predicted increased AHR signaling following HCoV-229E infection; AHR was also identified as a regulator of the transcriptional response to viral infection." (PMID 34446714, 2021). "This novel role of AHR in lipid biogenesis was also confirmed in non-infected Huh-7 cells and primary human hepatocytes, suggesting that AHR regulates store lipid reserves independently of viral infection." (PMID 33746961, 2021). "After silkworms were fed a high-concentration of BmNPV in this study, AhR was activated under the virus infection, which in turn acted on many different types of immunocytes." (PMID 32630275, 2020). "Aryl hydrocarbon receptor is a ligand-activated transcription factor, whose activation induces the expression of numerous genes and modulates host responses against viral infection." (PMID 30894203, 2019). "FICZ is a photoproduct of Trp seen upon UV irradiation, and it has received much attention because of its high-affinity binding to AHR and consequential regulation of the expression of many genes involved in viral infection and cancers." (PMID 31848275, 2019). "The few prior studies of AhR and viral infection have employed 2,3,7,8-tetrachlorodibenzo-ρ-dioxin (TCDD), an environmental pollutant." (PMID 30132758, 2018). "While increased PP2A/CAR activity promotes viral infection, decreased AhR activity results in uncontrolled immune homeostasis leading to dengue disease." (PMID 29447178, 2018). "In conclusion, ligation of the AhR with a single administration of TCDD given 5 days after virus infection significantly diminished HSV induced immunopathology." (PMID 22174686, 2011). "The AHR’s role in viral infections is still under investigation." (PMID 41596714, 2026). "Viral infection significantly inhibits the AHR signaling pathway, while consuming foods rich in indole compounds, such as cruciferous vegetables, can activate the AHR-Apelin signaling pathway in lung endothelium, maintain lung barrier function, and alleviate lung injury." (PMID 41155173, 2025). "There is a growing body of evidence that one of the essential molecular players modulating immune response to viral infection might be the AhR." (PMID 41150072, 2025). "In addition, we provide evidence that NFE2L2/KEAP1, FDFT1, and AHR are potentially druggable host targets with relevance for various viral infections." (PMID 38319076, 2024). "The effective utilization of AhR antagonists could significantly address the issue of multi-drug resistance in viral infections in the foreseeable future." (PMID 38680494, 2024). "The effects of other virus infections on the AHR signaling pathway have also been reported." (PMID 36829212, 2023). "Only upon viral infection is the wider regulatory capacity of endothelial AHR function realised, suggesting that in addition to ligand binding, AHR-driven expression programmes can be regulated by secondary signals derived from the disruption of lung homeostasis." (PMID 37587341, 2023). "On the basis of our findings on the role of AhR as a proviral host factor for SARS-CoV-2 replication, we hypothesized that the pathological damage caused by the virus infection in the lungs could be alleviated by inhibiting AhR activity." (PMID 37256962, 2023). "Indeed, it has been strongly suggested that AHR has a major impact on the interplay between environmental factors and viral infections." (PMID 36851583, 2023). "This review aims to discuss the potential effects of virus infections on AHR signaling pathways so that we may find a new strategy to minimize the adverse effects of the AHR pathway on diseases." (PMID 36829212, 2023).
viral infection (continued). "All evidence suggests that AHR plays a crucial role in virus infections." (PMID 36829212, 2023). "As this pathway is involved in IFN-I production and exocytosis, its inhibition by TIPARP-mediated ADP-ribosylation could indirectly link AhR to IFN-I inhibition in viral infections." (PMID 35203299, 2022). "Hence, based on its multiple effects on the immune response, the modulation of AHR signaling by environmental chemicals is likely to have important effects on the host response to viral infection." (PMID 33746961, 2021). "Viral infection activates AhR through an IDO1-AhR-IDO1-positive feedback loop, which eventually causes upregulation of downstream effectors, such as TCDD-inducible PARP (TiPARP), and enhances the expression of cytokines (e.g., interleukin IL-1β, IL-10, and TNF-α)." (PMID 34621138, 2021). "To elucidate the role of AHR signaling in cell-autonomous resistance to viral infection, we first analyzed AHR expression in untreated and HSV-1-infected human monocytic THP-1 cells and found that the level of the receptor mRNA was elevated following infection." (PMID 34668726, 2021). "However, little is known about activation of the KP and AHR in the setting of viral infections following BMT." (PMID 33491663, 2021). "Together, these results reveal a previously unknown function of AHR in promoting viral replication in vitro and suggest a potential intervention point for treating viral disease." (PMID 34668726, 2021). "Understanding the precise crosstalk between multiple chromatin modifiers, such as histone acetyltransferases/deacetylases and methyltransferases/demethylases, and the transcription factors Nrf2 and AhR upon IV infection is required to predict the consequences of viral infection accurately." (PMID 32689931, 2020). "In addition to the capability of AhR to be activated by metabolites, certain viral infections can activate AhR signaling, which in turns dampens the immune response against viruses, e.g., the suppression of IFN-I." (PMID 32957545, 2020). "AHR activation during development has a lasting impact on adaptive immune responses in the offspring, modulating T cell responses in several model systems, including viral infection." (PMID 30412605, 2018). "Exacerbation of viral infection may be related to the fact that AhR activation constrains the type-I interferon response." (PMID 30132758, 2018). "In this context, AhR activation during viral infections was reported to exacerbate pathogenesis." (PMID 30132758, 2018). "To determine whether AhR regulates IL-22 production from γδ T cells in viral infection, we measured the effects of AhR inhibitor on IL-22 expression in hepatic γδ T cells at 3 dpi." (PMID 28634408, 2017). "Therefore, activation of AhR signaling by viral infection may be a common phenomenon in the interaction between viruses and host cells." (PMID 40636257, 2025). "Interestingly, recent studies have suggested that the activation or depression of the AHR signaling pathway may play a role in the outcome of diverse human viral infections." (PMID 36851583, 2023). "Moreover, AhR is involved in the modulation of the host response to viral infection." (PMID 35056637, 2022). "Consequently, the ‘cytokine storm’ that occurs to many viral infections, including influenza and SARS-CoV-2, will be associated with the induction of IDO/TDO/kynurenine/AhR activation and therefore wills alterations in the immune response and decreases in the serotonergic and melatonergic pathway." (PMID 33562472, 2021). "Some viral-infection-related genes, such as Il1a and Srpk1, exhibited gains of stop codons, which may correlate with the ability of the AHR to serve as a pathogen carrier." (PMID 27172215, 2016).
viral infection (continued). "Interestingly, it was recently found that the lysosome–nucleus signaling pathway involves AhR that senses lysosomal cystine during ferroptosis in cancer cells, highlighting a novel correlation between lysosomes and AhR, which should be further investigated also during virus infections." (PMID 40006982, 2025). "Together, these data indicate that both the KP and AHR pathways are augmented in response to BMT and that they are further augmented following viral infection." (PMID 33491663, 2021). "In addition to modifying cellular susceptibility to SARS-CoV-2, treatment with AHR agonists might stimulate immune response in the treated cells without virus infection." (PMID 34404832, 2021). "For example reported transient AhR inhibition in acute viral infections without significant toxicity in murine models." (PMID 40636257, 2025). "Similar to what has been described in AhR’s regulation of differentiation in T cell populations, the role of AhR during viral infection can have both positive and negative consequences in host immune responses mounted against the virus." (PMID 37027342, 2023). "As an important environment-sensing ligand-inducible transcription factor, AHR plays a non-negligible role after virus infections." (PMID 36829212, 2023). "In addition, activation of AhR by TRYCATs, mainly KYN, affects immune resistance against viral infections and the airway basal cells of the lung epithelium, which are responsible for tissue repair." (PMID 35840908, 2022). "Recent reports have shown a role for AHR as a modulator of the intrinsic, innate and adaptive immune response to viral infections, with both positive and negative effects on host resistance and survival based on the experimental system used." (PMID 33746961, 2021). "Unlike bacteria, viruses are not thought to generate AhR ligands, therefore AhR has not frequently been studied in the context of viral infection." (PMID 30132758, 2018). "However, until recently, the impact of AHR on the host’s defense against viral infections has not been fully examined." (PMID 34668726, 2021). "However, clinical studies evaluating the safety and efficacy of targeting AHR for the treatment of viral infections are lacking." (PMID 33746961, 2021). "Several recent studies have shown that the activation of the AHR pathway reduces the virus-specific IgG titer, impairs the differentiation of CD4+ and CD8+ T cells, and increases inflammation, resulting in increased morbidity and mortality following viral infections." (PMID 34668726, 2021). "Another example is the aryl hydrocarbon receptor (AHR), a regulator of mucosal barrier function, activation of which during lung development enhances CD4+ T-cell responses to viral infections, and which more generally may influence immune responsiveness in the lungs." (PMID 29262847, 2017). "Thus, it is plausible that AhR activation during development can change epigenetic regulatory machinery in CD4+ T cells, leading to intrinsic differences when these cells respond to viral infection." (PMID 25051576, 2014). "Consequently, the use of AhR antagonists at the site of invasive infection may serve as a potential therapeutic approach for combating viral infections, as AhR plays a negative role in restricting cell-autonomous antiviral resistance." (PMID 38680494, 2024). "Indeed, it can be inferred that AHR may influence viral infection through impacting IRF-3 independent of IFN." (PMID 34668726, 2021).